SIRAL1 (SIR2 antiphage like 1)
Description:
May play a role in Cajal bodies formation.
Synonyms: FAM118B; SIRal; FLJ21103
Tractability: PROTAC: ubiquitination databases record sites on it.
Gene: Protein-coding gene on chromosome 11 (126,211,687 to 126,263,051, forward strand). Ensembl gene ENSG00000197798.
Subcellular location: Nucleus, Cajal body
Gene Ontology:
Molecular function: identical protein binding; protein binding
Cellular component: Cajal body
Genetic constraint (gnomAD): Loss-of-function variants: 19 observed, 34.8 expected, observed/expected ratio (o/e) 0.55, 90% interval 0.38 to 0.8. The upper end of that interval is the gene's LOEUF score, 0.8, which puts it in group 3 of 6, group 1 being the genes least tolerant of losing a copy. Missense variants: 303 observed, 412.24 expected, observed/expected ratio (o/e) 0.74, 90% interval 0.67 to 0.81. Synonymous variants: 132 observed, 155.66 expected, observed/expected ratio (o/e) 0.85, 90% interval 0.74 to 0.98.
Homologues: Orthologues: chimpanzee FAM118B (100% identical), macaque FAM118B (99% identical), mouse Fam118b (98% identical), rabbit FAM118B (98% identical), rat Fam118b (97% identical), dog FAM118B (97% identical), guinea pig FAM118B (97% identical), pig FAM118B (93% identical), tropical clawed frog fam118b (84% identical), zebrafish fam118b (77% identical). Paralogues in human: SIRAL2 (46% identical).
Diseases named in the same sentence as SIRAL1 in open-access papers:
SIRAL1 is named in the same sentence as 7 diseases in open-access papers, as found by Europe PMC text mining. Sharing a sentence is not in itself a finding about the gene and the disease.
SIRAL1 shares sentences with these, for which no sentence is quoted: meningioma (3 papers); brain tumors (2); cancer (1); ependymoma (1); nephrolithiasis (1); supratentorial ependymoma (1); tumor (1).